S100A2 (S100 calcium binding protein A2)
Diseases named in the same sentence as S100A2 in open-access papers (continued):
Sharing a sentence is not in itself a finding about the gene and the disease.
tumor (continued). "Since we have previously explored the role of S100A2 in predicting tumor immune microenvironment, we wondered whether S100A2 has any predictive effect in predicting the efficacy of immunotherapy for PC." (PMID 34887861, 2021). "However, concerning its role in the apoptosis, literature data shows an often contradictory role of S100A2 which in some cases works as a tumor suppressor, and in others, as a tumor promoter." (PMID 28686225, 2017). "Because S100A2 gene methylation is significantly more frequent in higher grade tumors, it may have a use as a marker of tumor progression." (PMID 26097874, 2015). "S100A2 is a calcium binding protein that has been repeatedly shown to be down regulated in a variety of cancers such as breast, and prostate and is considered to be a candidate tumor suppressor gene." (PMID 25884794, 2015). "Expression of S100A2 protein was found to be deregulated in a variety of tumor types." (PMID 25591983, 2015). "Moreover, S100A2 expression has been proposed as a prognostic biomarker for tumor recurrence in CRC patients treated with adjuvant chemotherapy after surgery." (PMID 26474385, 2015). "Thus, the ratio of 118:117 and 121:119 indicates the relative abundance of S100A2 protein in pooled cancerous tumor tissues compared to that of the control group." (PMID 25874882, 2015). "Taken together, in this context, a tumor-suppressor role for S100A2 is proposed." (PMID 25874882, 2015). "Our data also suggest that EGLN1 and S100A2 are likely to act at later stages of the metastatic cascade (extravasation, seeding, survival, and/or growth of the tumor cells in secondary sites) because, although the primary tumors are very invasive, they failed to colonize distant organs." (PMID 24618895, 2014). "S100A2 is a known tumor suppressor that controls tumor progression and growth." (PMID 21457566, 2011). "Patterns of methylation observed for S100A2 were complex; evidence of methylation was observed in all primary tumours tested; however, considerable variation was seen in both the number of CpG residues affected and the extent of methylation observed at individual CpG residues." (PMID 17579622, 2007). "S100A2 has been postulated in certain studies to play a suppressor role in tumour development, as it shows reduced expression in a range of cancer types, while other investigators have been unable to show any clear difference in methylation patterns between tumours and normal tissue." (PMID 17579622, 2007). "The potential clinical significance of the expression of myoepithelial/basal genes in ER-positive tumours has been highlighted by recent data showing that the promoter DNA methylation of the classic myoepithelial marker S100A2 is correlated with a poor prognosis in ER-positive tumours." (PMID 17014703, 2006). "A similar pattern of expression for S100A2 has been reported in other tumour types." (PMID 15467767, 2004). "This patient also showed strong expression of S100A2 in the tumour tissue." (PMID 15467767, 2004). "Among them, CD8+T cells, which have demonstrated the greatest efficacy in tumor eradication, exhibited a marked reduction in the high S100A2 expression group, providing a partial explanation for the unfavorable prognosis observed in patients with high S100A2 expression." (PMID 38260844, 2023). "Moreover, tumor cells from this stage IV sample show upregulation of genes related to EMT, angiogenesis, and metabolic pathways, including those that have been previously associated with tumor progression such as MMP1, S100A2, TSPAN8, and IGFBP2." (PMID 33170151, 2020). "Expression profiles of S100A2 indicate that it may be a candidate tumor suppressor gene." (PMID 26097874, 2015).
tumor (continued). "Such evidence has led to the belief that S100A2 may be candidate tumor suppressor gene." (PMID 26097874, 2015). "Contrary to the hypothesis that S100A2 is a tumour suppressor, no somatic mutations were identified in the coding sequence in 44 tumours." (PMID 15467767, 2004). "The unusual expression of genes like SERPINB5 and S100A2 in differentiated preinvasive cells (and subsequently in tumours) may therefore indicate that a failure to appropriately inactivate stem cell-associated sequences, perhaps by epigenetic modification, is an important proneoplastic mechanism." (PMID 15467767, 2004). "In addition to examining expression in normal and tumour tissue in this series, we also sought to examine expression in relation to preneoplasia, histology, and clinical outcome, in an attempt to further characterise the expression of S100A2 in NSCLC." (PMID 15467767, 2004). "Our study demonstrates that in ccRCC, S100A2 functions as a cofactor assisting the transcription factor HNF1A in promoting GLUT2 expression, thereby enhancing glycolysis and driving tumor progression." (PMID 40011447, 2025). "Analyzing the correlation between S100A2 mRNA expression and ccRCC stage in the TCGA dataset via GEPIA 2 website indicated an upregulation of S100A2 at the advanced tumor stage." (PMID 40011447, 2025). "S100A2, S100A11, and S100A14 are three S100s with complex roles in cancer, as they have been described as either tumor suppressors or tumor promoters." (PMID 37627239, 2023). "We also observed many significant changes in immune and inflammatory response genes across murine tumour genotypes with notable correlations of EDC genes and immune cell markers such as S100a2 that we also observed in human samples." (PMID 37626054, 2023). "S100P, S100A2 and MMP12 were expressed higher in tumor tissues, compared with normal tissues (P < 0.001), while the opposite was true for DEFA5 expression (P < 0.05)." (PMID 35831362, 2022). "S100A2, S100P and MMP12 were all over expressed in tumor tissues based on paired (P < 0.01) and unpaired expression analysis (P < 0.001)." (PMID 35831362, 2022). "miR-325-3p overexpression in breast cancer tumor cells enhances tumor cell proliferation and invasion, and EMT development by suppressing S100A2 expression in vitro." (PMID 35885660, 2022). "However, the underlying mechanism by which S100A2 promotes the progression of PC has not been fully revealed, which is also the main content of this study, especially the relationship between S100A2 and the tumor immune microenvironment." (PMID 34887861, 2021). "Genes related to tumor progression, including matrix metallopeptidase 1 or MMP1, S100 calcium binding protein A2 or S100A2, tetraspanin 8 or TSPAN8, and insulin like growth factor binding protein 7 or IGFBP7 were upregulated in GSM3516665-subgroup 2." (PMID 33170151, 2020). "61, 83 and 83% of tumours showed moderate to strong staining for S100A4, S100A6 and S100A14, respectively, whereas only 22% were positive for S100A2." (PMID 31123345, 2019). "In view of miRNA functional mechanism and oncogenic roles of GJB2, S100A2 and SPOCK2, upstream miRNAs of the three genes should be tumor suppressive miRNAs." (PMID 31794425, 2019). "Meghnani and colleagues also reported an up‐regulation of the RAGE ligands S100B, S100A2, S100A4, S100A6 and S100A10 in RAGE overexpressing tumours." (PMID 26928771, 2016). "Verification studies using qRT-PCR, immunoblot and IHC assays confirmed that the expressions of S100A2, POSTN, FN1 and KRT17 were, indeed, significantly increased in tumor tissues." (PMID 25874882, 2015).
tumor (continued). "Several common target genes in the networks were down-regulated in both wt and mt tumor cells, such as ITGA5 and S100A2 (adhesion and migration), SERPINE1 (angiogenesis), CDKN1A (growth arrest), and PLAU and SERPINE5 (proteolysis)." (PMID 24069219, 2013). "A total of 15 genes (AIM1, ARF, CCNA1, MGMT, hMLH1, PGP9.5, S100A2, APC, RAR-β2, ER-α, ER-β, MCAM, VGF, FKBP4 and SSBP2) were analysed for promoter methylation using QMSP in 57 tumour samples, comprising 43 SEs and 14 NSEs, and 23 NT samples." (PMID 22068818, 2012). "The MCC marker CCER2 was strongly expressed in the tumor, while epidermal MCC-associated genes, such as S100A2 and CALML3/5, were largely absent in MCC cells, but highly expressed in the epidermis." (PMID 41131107, 2025). "Based on the previous literature, we hypothesize that S100A2 may affect LNM by suppressing immunity and regulating tumor glycolysis." (PMID 38146045, 2024). "Moreover, KRT15, CALML5, and S100A2 have been described as having stem cell functions and EMP regulation, suggesting both tumor-promoting and tumor-suppressive roles." (PMID 39225101, 2024). "We speculate that FOS+ S100A2+ Teff subpopulation promote T-cell infiltration and migration toward tumor regions by increasing S100A2 levels through FOS-mediated transcriptional regulation, thereby inhibiting tumor growth and development." (PMID 39234254, 2024). "However, correlations were observed between S100A2 and S100A7 (R = 0.48), S100A11 (R = 0.54), S100A14 (R = 0.50), S10016 (R = 0.61) and S100P (R = 0.85), when comparing transcript levels from the tumor array." (PMID 37627239, 2023). "However, in the tumor array, positive correlations were observed between S100A14 and S100A2 (R = 0.50), S100A4 (R = 0.55), S100A6 (R = 0.45), S100A7 (R = 0.47), S100A11 (R = 0.65), S100A16 (R = 0.57) and S100P (R = 0.66)." (PMID 37627239, 2023). "In addition, correlations were also noted in the tumor array between S100A11 and S100A2 (R = 0.54), S100A4 (R = 0.46), S100A6 (R = 0.49), S100A13 (R = 0.67), S100A14 (R = 0.65), and S100A16 (R = 0.78)." (PMID 37627239, 2023). "In the current study, we can only observe S100A2 cytoplasmic expression from the TMAs tumour core of CRC patients, therefore a nuclear expression of S100A2 should also be investigated in both tumour core and invasive front to understand the role of S100A2 regarding its localisation in tumour cells." (PMID 37476187, 2023). "We hypothesized that CXCL6, S100A2, and SDC1 lead to tumor progression and immune escape by raising gamma delta T cells and reducing CD8+T cells, but this hypothesis needs further verification." (PMID 35432485, 2022). "Overall, the current research suggests that S100A2 overexpression is a biomarker of tumor progression or negative prognosis in PC patients." (PMID 34527585, 2021). "The most notable examples of down-regulated genes were GUCA2B (FC = 187), TMIGD1 (FC = 129) and CA1 (FC = 121), while CST1 and S100A2 (FC = 131/88.7, respectively) were highly expressed in tumours but not in normal tissue." (PMID 30231850, 2018). "Recent studies have also shown that TGF-β1 can regulate the expression of S100A4, and cancer cells invasion mediated by TGF-β1 could be inhibited by S100A2 silence, indicating that S100A4 might be the molecular target of TGF-β1 in tumor metastasis." (PMID 24885536, 2014). "As one of the reasons, S100A2 was a responsible for tumor cell migration in some tumor cells in vitro, suggesting that A100S2 might have different unknown action mechanisms in each tumor." (PMID 35885660, 2022). "High S100A2 expression has been observed in the metastatic site but not in the primary tumor, suggesting that it may be a marker of tumor metastasis." (PMID 34527585, 2021).
tumor (continued). "A study involving 424 normal and tumor tissues of various origin showed that while in normal non-epithelial tissues have low level of S100A2 expression, in normal epithelial tissue its expression is present but decreases in tumors of epithelial origin concurrently with loss of keratin K14." (PMID 26097874, 2015). "Cells in which CYR61, EGLN1, or S100A2 were knocked down formed highly invasive (white arrow) and desmoplastic tumors resembling the control tumors, suggesting that these proteins did not influence tumor invasion or fibrosis." (PMID 24618895, 2014). "Most tumours strongly expressed the ΔNp63 transcript, the product of which is a putative regulator of S100A2 transcription and while all but one of the tumours positive for ΔNp63 expressed S100A2, others negative for this regulator also expressed the gene." (PMID 15467767, 2004). "All tumours and non-tumour sites were investigated for S100A2 expression." (PMID 15467767, 2004). "Our study is the first to demonstrate that S100A2 overexpression may promote tumour progression through regulating ECM‐receptor interaction, and HIF‐1α transcription factor network in PC, which provides important rational for future experimental study about S100A2." (PMID 33580614, 2021). "However, it has not been reported whether the other four genes, NCAPG, S100A2, DERL3, and COL22A1, exert any biological role in the interaction between tumor and immune cells." (PMID 34136486, 2021).
cancer (70 papers, 2000 to 2026). A tumor composed of atypical neoplastic, often pleomorphic cells that invade other tissues. "Taken together, these data underscore the crucial role of S100A2 in regulating the Warburg effect, a metabolic shift associated with cancer aggressiveness." (PMID 40011447, 2025). "Further research is warranted to elucidate the precise mechanisms underlying the contradictory roles of S100A2 in various cancer contexts, providing valuable insights for potential therapeutic strategies." (PMID 40011447, 2025). "Concordant with our data, overexpression of S100A2 has been associated with poor clinical outcome in colorectal and oral cancers." (PMID 27935967, 2016). "S100A2 is implicated in metastasis development in several cancers." (PMID 25999659, 2015). "The role of S100A2 in tumors has exhibited a dual nature, functioning as either a cancer promoter or a cancer suppressor through diverse molecular mechanisms." (PMID 40011447, 2025). "Mechanistically, we demonstrate that S100A2 accelerates cancer progression through its interaction with the transcription factor HNF1A, leading to activating GLUT2 transcription." (PMID 40011447, 2025). "Employing immunofluorescence experiments, we determined the subcellular localization of S100A2 in ccRCC, revealing its predominant presence in the nucleus and cytoplasm of cancer cells." (PMID 40011447, 2025). "Further investigations into the interplay between S100A2 and other metabolic regulators across different cancer types are necessary to uncover potential therapeutic targets." (PMID 40011447, 2025). "Previous work in our lab has demonstrated that inhibiting the cancer-promoting effects of S100A2 in tumors by blocking its interaction with KPNA2 can be effective." (PMID 40011447, 2025). "FN1 can drive the occurrence and progression of various cancers through metabolic reprogramming, while the overexpression of S100A2 can enhance glycolysis and promote cancer cell proliferation." (PMID 41176774, 2025). "Many of these genes, such as VIM, FOSL2, PTN, GPR3, SIAH2, UPP1, S100A2 are associated with cell migration and epithelial-mesenchymal transition (EMT) in several cancers." (PMID 36850002, 2023). "In cancer cell lines, S100A2 presented the lowest transcript level among the 13 selected S100 genes." (PMID 37627239, 2023). "Although the function of this protein requires elucidation, S100A2 has been described as a potential predictive marker in various types of cancer 10-16." (PMID 37476187, 2023). "Previous studies indicated that KRT6A and its downstream gene S100A2 were the biomarkers and therapeutic targets for various cancers, including CRC." (PMID 37647260, 2023). "Based on our findings, S100A2 levels in the cancer group significantly increased compared with the normal group, and high S100A2 levels led to poor prognoses and disease-free survival." (PMID 37758734, 2023). "S100A2, a member of the S100 protein family, is abnormally expressed and plays a vital role in multiple cancers." (PMID 35042454, 2022). "In particular, there exists a need to elucidate expression alterations of S100A2 in early and advanced stages of malignant tumors, in addition to determining the actual impact of S100A2 on their prognosis." (PMID 35885660, 2022). "Despite the analysis of S100A2 in cancers, there are only a few studies focused on inflammatory diseases and benign tumors." (PMID 35885660, 2022). "We obtained the protein expression pattern of S100P and S100A2 in different cancers based on the HPA database." (PMID 35831362, 2022). "KDM5C recovers S100A2 expression through histone demethylation to impair the proliferation and migration of cancer cells, suggesting that histone methylation leads to the impairment of S100A2 expression in tumors." (PMID 35885660, 2022). "A pan-cancer analysis of S100A2 was performed, showing that PC experienced one of the most remarkably increase of S100A2 expression among all types of cancer." (PMID 34887861, 2021).